TF (transferrin)
Diseases named in the same sentence as TF in open-access papers (continued):
Sharing a sentence is not in itself a finding about the gene and the disease.
hemorrhagic stroke (5 papers, 2014 to 2024). A stroke caused by a bleed on the brain. "Second, subendothelial TF expression varies among vascular beds, a property that may in part explain the increased gastrointestinal bleeding, but the decreased incidence of hemorrhagic stroke, associated with dabigatran relative to warfarin." (PMID 24497951, 2014). "Importantly, compared with the contralateral brain hemisphere, both ischemic and hemorrhagic stroke increased the protein levels of iron-storage ferritin and the iron-binding and carrier transferrin in the ipsilateral hemisphere." (PMID 38001798, 2023).
multiple sclerosis (5 papers, 2014 to 2022). A progressive autoimmune disorder affecting the central nervous system resulting in demyelination. "Interestingly, members of these TF families are also at play in OPCs in the adult brain in a murine multiple sclerosis model, reinforcing our data." (PMID 36513635, 2022). "Because of the complexity and heterogeneity of multiple sclerosis, it is difficult to find a single marker for all of the processes involved in the origin and progression of the disease, so the development of a panel of biomarkers is desirable, and anti-transferrin antibody could be one of these." (PMID 25517032, 2014).
myeloma (5 papers, 2014 to 2025). "KabC-platelets, surface-coupled with transferrin and Cy7, or chlorin-e6, and injected in immuno-compromised mice were shown to accumulate specifically in sub-cutaneous and intra-cranial myeloma xenotransplants." (PMID 27049725, 2016). "After being injected into mice bearing RPMI8226 cell-derived myeloma xenotransplants, the nanoplatelets with transferrin–Cy7 accumulated in the sub-cutaneous and intra-cranial myeloma xenotransplants, where they generated intense NIRF signals that allowed performing high-contrast imaging." (PMID 36836127, 2023). "A further control study was conducted to show the labeling of intra-cranial myeloma xenotransplants with KabC-platelets was dependent on interactions between transferrin molecules on the surface of the platelet and transferrin receptors on the surface of the tumor cell." (PMID 27049725, 2016). "Next, we explored the diagnostic (in vivo imaging) and therapeutic potential of EPI-loaded nanoplatelets coupled with transferrin and Cy7 by analyzing their interactions with RPMI8226 cells within myeloma xenotransplants in immuno-compromised mice." (PMID 36836127, 2023). "Taken together, in vivo imaging studies show injected KabC-platelets coupled with transferrin and Cy7 (test platelets) accumulate within RPMI8226 cell-derived myeloma xenotransplants." (PMID 27049725, 2016). "KabC-platelets, surface-coupled with transferrin and Cy7, were shown using in vivo fluorescence imaging to accumulate within RPMI8226 cell-derived myeloma xenotransplants in immuno-compromised mice." (PMID 27049725, 2016). "In a retrospective study of 5259 patients with multiple myeloma (MM) at the University of Arkansas, we identified adverse prognostic factors, including delayed MM-diagnosis-to-ASCT duration, high serum ferritin, and low transferrin levels." (PMID 38539451, 2024). "The reactions used to repurpose human platelets for targeted imaging of myeloma were optimized using FACS and fluorescence microscopy - repurposed platelets configured with KabC, EPI, transferrin and Cy7 were prepared within an hour of receiving outdated human platelets." (PMID 27049725, 2016). "The test results also showed that the nanoplatelets functionalized with transferrin and Cy7 and injected in mice bearing RPMI8226 cells-derived myeloma xenotransplants accumulated in the tumor tissue and could be used for high-contrast in vivo NIRF imaging of early-stage tumors." (PMID 36836127, 2023).
osteosarcoma (5 papers, 2021 to 2025). A usually aggressive malignant bone-forming mesenchymal neoplasm, predominantly affecting adolescents and young adults. "We demonstrate that knockdown of RAB23 in human osteosarcoma cells (MG-63) also reduces transferrin uptake, and that this can be normalized by overexpressing of RAB23." (PMID 40261407, 2025). "We normalized transferrin uptake in RAB23 knockdown human osteosarcoma cells (MG-63) by overexpressing RAB23." (PMID 40261407, 2025). "Similar to RAB23 deficient mouse calvaria derived primary cells, we demonstrate reduced transferrin uptake in human osteosarcoma cells (MG-63) where the expression of RAB23 was reduced by siRNA-mediated knockdown." (PMID 40261407, 2025). "Many of these time point-specific patterns of TF gene expression were also observed in another metastatic osteosarcoma cell line (MNNG-HOS) when the cells were grown within lung explants." (PMID 37938582, 2023). "In the TF-mRNA network, GATA3, which regulates 5 key targets, is an oncogenic factor and has been reported to be lowly expressed in osteosarcoma, inhibiting OS progression and metastasis by regulating slug." (PMID 40831924, 2025). "Proteomic sequencing analysis indicated that ferroptosis-related proteins, particularly transferrin (TF) and NADPH oxidase 2 (NOX2), were involved in simvastatin's inhibition of osteosarcoma." (PMID 39830135, 2025). "Among them, the expression of MYH6 and SULT4A1 in osteosarcoma was higher than that in control group, while the expression of LIPE, ACTG2, KLF4, and TF was decreased." (PMID 34104648, 2021).
pneumonia (5 papers, 2012 to 2024). An acute, acute and chronic, or chronic inflammation focally or diffusely affecting the lung parenchyma, caused by an infection in one or both of the lungs (by bacteria, viruses, fungi, or mycoplasma.). "The colistin concentration is supposed to be elevated in mice treated with CCM-CL for CRPA pneumonia, as iron in the CCMs is chelated in the lungs, where transferrin is highly expressed." (PMID 37237739, 2023). "The preoperative serum transferrin level is a possible predictive marker of postoperative pneumonia after esophageal surgery." (PMID 33860145, 2021).
preeclampsia (5 papers, 2022 to 2025). Preeclampsia is a hypertensive disorder of pregnancy that is characterized by new-onset hypertension with proteinuria presenting after 20 weeks of gestation, and depending on mild or severe forms may initially present with severe headache, visual disturbances, and hyperreflexia. "One study compared stretching to walking to prevent HDPs among pregnant women with prior HDPs,54 but while it observed some differences in transferrin levels and rates of preeclampsia vs. gestational hypertension, these results lacked clinical significance." (PMID 40778148, 2025).
Thromboembolism (5 papers, 2015 to 2022). The formation of a blood clot inside a blood vessel that subsequently travels through the blood stream from the site where it formed to another location in the body, generally leading to vascular occlusion at the distant site. "Indeed, several reports already documented cases of DIC and thromboembolism occurring after the infusion of TF/CD142-expressing MSC products, particularly in preactivated patients." (PMID 32574263, 2020).
thyroid cancer (5 papers, 2014 to 2025). "Transferrin-modified hollow mesoporous silica nanoparticles (HMSNs) have been used for the targeted delivery of sorafenib in drug-resistant thyroid cancer TPC-1 and BCPAP cells." (PMID 34944814, 2021). "In thyroid carcinoma cells, the increases in apoptosis through the knockdown of LCN2 were found to be canceled by the addition of Ferric ions or iron-loaded transferrin." (PMID 27168162, 2016).
vitamin D deficiency (5 papers, 2016 to 2024). A nutritional condition produced by a deficiency of VITAMIN D in the diet, insufficient production of vitamin D in the skin, inadequate absorption of vitamin D from the diet, or abnormal conversion of vitamin D to its bioactive metabolites. "In contrast to our study, an earlier study including 22-month-old Asian infants reported that vitamin D deficiency (25(OH)D <25 nmol/L) was associated with lower serum iron concentrations, but not transferrin levels." (PMID 35405984, 2022).
Acidosis (4 papers, 2015 to 2020). Abnormal acid accumulation or depletion of base. "Acidosis reduces the binding of iron to transferrin; in turn, available free iron helps in proliferation of the Mucorales." (PMID 27200123, 2016). "Acidosis disrupts iron binding of transferrin, resulting in increased proportion of unbound iron, which may promote growth of the fungus." (PMID 26758904, 2016).
age-related macular degeneration (4 papers, 2011 to 2024). Age-related loss of vision in the central portion of the retina (macula), secondary to retinal degeneration. "Preclinical studies have shown that TF is expressed in human conjunctiva and is closely associated with the occurrence and progression of pterygium and age-related macular degeneration." (PMID 39742259, 2024). "We recently showed that transferrin level was associated with age-related macular degeneration (AMD)." (PMID 24350254, 2013). "The TF expression is detected on endothelial cells of pathological capillary blood vessels associated with solid tumours, wet macular degeneration (wMD) and endometriosis; however, TF is not expressed on endothelial cells of normal blood vessels." (PMID 21427724, 2011).
Allergy (4 papers, 2012 to 2026). An allergy is an immune response or reaction to substances that are usually not harmful. "Whilst the causative factor of TF in these regions of the Solomon Islands remains unknown, it seems unlikely that the majority of clinical signs can be attributed to Ct, any other bacterial pathogen, or allergies; further work may be required to determine the aetiology of the disease." (PMID 30440006, 2018). "Indeed, in our presented case, the time between referral to allergy/immunology and beta‐2‐transferrin testing positivity was 219 days." (PMID 41509503, 2026).
Arterial thrombosis (4 papers, 2018 to 2024). The formation of a blood clot inside an artery. "The authors not only correlated the loss of sirtuins with the promotion of arterial thrombosis, but also demonstrated that their inhibition is linked to an elevated level of TF." (PMID 30546314, 2018). "TMAO upregulates vascular endothelial TF expression via the NF-κB signaling pathway and increases TF activity and thrombin production, promoting arterial thrombosis." (PMID 39595639, 2024). "This study demonstrates that IS promotes arterial thrombosis and prothrombotic state that is connected with an increased level of complex TF/VII, PAI-1, and platelet activation, as well as decreased aortic contents of SIRT1 and SIRT3." (PMID 30546314, 2018). "Finally, ticagrelor inhibited TF expression and activity in human aortic endothelial cells, independently of P2Y12 and ENT-1, and decreased thrombosis and endothelial TF expression in a photochemical mouse model of arterial thrombosis." (PMID 32092903, 2020).
asthma (4 papers, 2021 to 2025). "Accordingly, it has been shown that in asthma and COPD, increased TF expression leads to TLR2 activation and, ultimately, inflammation." (PMID 38018577, 2023).
chronic pancreatitis (4 papers, 2017 to 2022). A chronic inflammatory process causing damage and fibrosis of the pancreatic parenchyma. "While testing the concentrations of transferrin isoforms, a statistically significant decrease in the 5-sialoTf concentrations in the acute and chronic pancreatitis groups was observed in comparison with the control group (p = 0.003 and p = 0.026, respectively)." (PMID 35329964, 2022). "Total transferrin concentrations were significantly lower in the AP and CP groups in comparison with the controls (p < 0.001 and p = 0.002, respectively) and in the acute pancreatitis group, it was significantly lower than that in the chronic pancreatitis group (p = 0.028)." (PMID 35329964, 2022). "Given that chronic pancreatitis is a risk factor for PDAC and that an inflammatory environment can directly promote tumor initiation, we employed here TD protocols P2 and a third protocol (P3, based on a combination of IGF-1, SCF and transferrin) for the generation of insulin-expressing cells." (PMID 34572891, 2021). "In particular, increased sLex expression on α1-acid glycoprotein occurs in both cancer and chronic pancreatitis, while increased expression on haptoglobin, fetuin, antitrypsin and transferrin is associated only with chronic pancreatitis, not with pancreatic cancer." (PMID 28241499, 2017). "In the chronic pancreatitis group, the mean values of GGT, ALP and CRP were significantly higher, but total transferrin was significantly lower in the CP group than that in the controls." (PMID 35329964, 2022). "In conclusion, the alterations in transferrin isoform profile in acute and chronic pancreatitis are not organ specific." (PMID 35329964, 2022). "In conclusion, we showed the changes in transferrin isoform profile in acute and chronic pancreatitis, which are not organ specific, but specific to the pathogenesis of the disease, in this case, inflammation." (PMID 35329964, 2022). "There were no significant changes in transferrin isoforms between the acute and chronic pancreatitis groups, and between the edematous and necrotizing forms of the disease." (PMID 35329964, 2022).
dengue (4 papers, 2009 to 2023). "In DHF, fibronectin, HPX, and transferrin levels significantly rise in all three phases compared to Dengue Fever (DF)." (PMID 38022615, 2023). "Finally, to further confirm these results, we performed glycoprofiling of intact plasma transferrin using mass spectrometry in five dengue patients with the highest plasma sialidase activity in the functional assay." (PMID 30849118, 2019). "Sialidase activity and plasma transferrin glycosylation of patients with dengue." (PMID 30849118, 2019). "Indeed, no detectable activity of neuraminidase was present in plasma of dengue patients and no desialylation was found of plasma transferrin." (PMID 30849118, 2019). "This was further supported by the fact that sialidase activity in plasma of dengue patients was not increased, that plasma of dengue patients failed to induce desialylation of platelets of healthy volunteers and that plasma proteins (transferrin) of dengue patients were not desialylated." (PMID 30849118, 2019). "HPX levels may help determine the severity of the illness, discriminate between dengue hemorrhagic fever (DHF) and uncomplicated dengue fever (DF), which would aid in diagnosis and treatment; and fibronectin, HPX and transferrin were found to be significantly decreased in DHF." (PMID 26175690, 2015).
folate deficiency (4 papers, 2010 to 2025). A nutritional condition produced by a deficiency of FOLIC ACID in the diet. "Serum transferrin and red blood cell folate are better indicators of iron and folate deficiency which our budget could not afford." (PMID 20537176, 2010).
gestational diabetes (4 papers, 2008 to 2025). Carbohydrate intolerance first diagnosed during pregnancy. "In placentae from normal pregnancies, the expression of transferrin in the syncytium was significantly lower (p < 0.001) when compared to placentae from abnormal ones (gestational diabetes, pregnancy induced hypertension, drug abuse)." (PMID 18597674, 2008). "In support of our findings, a previous study reported increased transferrin expression in the syncytiotrophoblast of pregnancies complicated by maternal drug abuse, gestational diabetes or pregnancy-induced hypertension, suggesting that this may represent a response to intrauterine stress." (PMID 31752878, 2019).
gout (4 papers, 2018 to 2024). A condition characterized by painful swelling of the joints, which is caused by deposition of urate crystals. "Research across various regions has identified a consistent positive correlation between elevated serum ferritin, transferrin, and iron levels and the risk of hyperuricemia and gout attacks." (PMID 39022306, 2024). "Additionally, studies utilizing serum iron, ferritin, transferrin saturation, and transferrin levels have revealed a positive relationship between hereditary high iron status and gout incidence." (PMID 39022306, 2024). "Regarding gout, both serum iron and TSAT showed a positive causal relationship (OR [95% CI] values of 1.3357 [1.0915-1.6345] and 1.2316 [1.0666-1.4221] for serum iron and TSAT, respectively), while transferrin exhibited a protective causal relationship (OR [95% CI], 0.8563 [0.7802-0.9399])." (PMID 39345879, 2024). "For gout, gene-predicted serum iron and TSAT exhibited a positive correlation with the risk (OR [95% CI], 1.3357 [1.0915-1.6345] and 1.2316 [1.0666-1.4221], respectively), whereas transferrin showed a negative correlation (OR [95% CI], 0.8563 [0.7802-0.9399])." (PMID 39345879, 2024).
hemoglobinopathies (4 papers, 2019 to 2025). "Ret-Hb has the highest overall sensitivity and specificity compared with ferritin, transferrin saturation, and MCV for predicting the absence of bone marrow iron stores, provided MCV < 100 fL and in the absence of hemoglobinopathies." (PMID 36558502, 2022).
hemorrhage (4 papers, 2019 to 2023). Loss of blood from the vascular compartment to the exterior or into nonvascular body space as a result of rupture or severance of the blood vessels. "The infarct size of the IS mice was double that of hemorrhage in ICH mice, but both groups showed similar body weight loss, edema, and increased ferritin and transferrin levels in the ipsilateral brain hemisphere." (PMID 38001798, 2023). "Expanded erythropoiesis, as after hemorrhage or erythropoietin treatment, blocks hepcidin through an acute reduction of transferrin saturation and the release of the erythroblast hormone and hepcidin inhibitor erythroferrone." (PMID 31649559, 2019).
HIV-1 infection (4 papers, 2015 to 2018). The type species of lentivirus and the etiologic agent of acquired immunodeficiency syndrome (AIDS). "Instead, transferrin uptake remains fully functional in all these cell lines despite the pretreatment of these cells with dynasore at concentrations that partially block HIV-1 infection." (PMID 31058179, 2018). "During the course of HIV-1 infection there is an increase in TF expression on the surface of activated monocytes." (PMID 28749986, 2017). "TF variants were also not observed to have enhanced replicative capacity in monocyte-derived dendritic cells, an in vitro model for dendritic cells, which may act as an initial target cell for establishment of HIV-1 infection." (PMID 26378795, 2015). "Therefore, the inhibition on HIV-1 infection by dynasore in these cell lines is due to an effect that is independent of transferrin endocytosis." (PMID 31058179, 2018).
Immunodeficiency (4 papers, 2020 to 2025). Failure of the immune system to protect the body adequately from infection, due to the absence or insufficiency of some component process or substance. "Earlier investigations on IDA predominantly focused on changes in blood iron-related markers, such as ferritin, transferrin, and serum iron, and their associations with systemic inflammation and immune dysfunction." (PMID 40149653, 2025). "TF overexpression in human TB and other infectious diseases is more likely linked to protective immune responses, while its downregulation is more often related to immune deficiencies." (PMID 34869715, 2021).
Intellectual disability (4 papers, 2018 to 2024). "The clinical phenotypes are dramatic and overlap in intellectual disability, seizures, brain structural abnormalities, low to undetectable Mn, and impaired transferrin glycosylation." (PMID 32753748, 2020). "It is important to note that, in addition to the immune system aberrations, neurological problems in the patient (intellectual disability, failure to thrive, and facial dysmorphism) are consistent with the importance of iron-transferrin-TfR1 axis in the nervous system." (PMID 38270687, 2024).